DPP4 (dipeptidyl peptidase 4)
Diseases named in the same sentence as DPP4 in open-access papers (continued):
Sharing a sentence is not in itself a finding about the gene and the disease.
type 2 diabetes (continued). "The management of type 2 diabetes has evolved significantly with the advent of incretin-based therapies, particularly dipeptidyl peptidase-4 inhibitors and glucagon-like peptide-1 receptor agonists." (PMID 40607140, 2025). "By using around 10−4 as a criterion to select SNPs as IVs, muti-GRAPPLE shows that DPP4 gene expression at the mRNA level affects HF independent to type-2 diabetes (effect: 0.25; CI, 0.01–0.45; p=0.04 for UKB." (PMID 40904650, 2025). "While various studies evaluated tolerability, safety of DPP-4 inhibitors in patients with impaired kidney function and type 2 diabetes mellitus, information about the outcomes of clinical trials pertaining to primary kidney disease is currently unavailable." (PMID 40337567, 2025). "By 2020, both GLP‐1 receptor agonists and SGLT‐2 inhibitors were more commonly prescribed in incident patients with type 2 diabetes than DPP‐4 inhibitors." (PMID 40464139, 2025). "Using the JMDC payer database, we identified new users of sodium-glucose cotransporter-2 (SGLT2) inhibitors or dipeptidyl peptidase-4 (DPP-4) inhibitors as the first choice of treatment for type 2 diabetes." (PMID 41041642, 2025). "BP can arise as a primary idiopathic disorder (classic BP, cBP) or in association with pharmacologic treatment using dipeptidyl-peptidase 4 (DPP4) inhibitors, commonly known as gliptins, used in the management of type 2 diabetes (DPP4i-associated BP)." (PMID 41373842, 2025). "Several reports have shown the efficacy of the combination of SGLT2 and DPP-4 inhibitors in patients with type 2 diabetes." (PMID 39865301, 2025). "In people aged ≥ 60 years with type 2 diabetes, SGLT2 inhibitor versus DPP4 inhibitor initiation was associated with lower risk of all-cause dementia, and the observed risk reduction was greater with continuous use." (PMID 41420258, 2025). "While the cardiovascular safety of DPP-4 inhibitors has been established in the general type 2 diabetes mellitus (T2DM) population, the cardiovascular safety in DM1 patients, who already have a high risk of arrhythmias and heart failure, remains uncertain." (PMID 41018201, 2025). "A target trial emulation using Medicare data investigated the risk of suicidal ideation and behaviors in older adults with type 2 diabetes associated with GLP-1 RA compared to SGLT2 inhibitors and DPP-4 inhibitors." (PMID 39844933, 2025). "In our study, we demonstrated consistent clinical benefits of SGLT2 inhibitors compared to DPP4 inhibitors in patients with AF and type 2 diabetes using a nationwide cohort with long-term follow-up." (PMID 39919084, 2025). "Early studies on patients with type 2 diabetes treated with incretin therapy including GLP-1s and dipeptidyl peptidase-4 (DPP4) inhibitors did demonstrate an association between drug usage and the development of pancreatitis." (PMID 40149944, 2025). "Does the efficacy of sodium-glucose cotransporter 2 inhibitors, glucagon-like peptide-1 receptor agonists, and dipeptidyl peptidase 4 inhibitors vary by age and sex among individuals with type 2 diabetes?" (PMID 39899304, 2025). "The sodium-glucose transport protein 2 (SGLT2) inhibitor empagliflozin and the dipeptidyl peptidase 4 (DPP-4) inhibitor linagliptin are well-established treatments for adults with type 2 diabetes (T2D)." (PMID 39373938, 2025). "Among 114,166 patients with type 2 diabetes and AF, a total of 23,467 new medication users were included in the cohort analysis (21,816 new users in the DPP4 inhibitor group and 1,616 new users in the SGLT2 inhibitor group)." (PMID 39919084, 2025). "Among the patients with type 2 diabetes (n = 34), 21 (61.8%) were treated with metformin, 8 (23.5%) with insulin, 6 (17.6%) with DPP-4 inhibitors, and 2 (5.9%) with sulfonylureas." (PMID 40564192, 2025). "Glucagon-like peptide-1 receptor (GLP1R) agonists, GLP1 analogues that are resistant to degradation by dipeptidyl peptidase 4, are used to treat type 2 diabetes mellitus (T2DM)." (PMID 40770700, 2025).
type 2 diabetes (continued). "Given their widespread use and overall safety profile, DPP-4 inhibitors remain a first-line or second-line treatment for many Japanese individuals with type 2 diabetes, though careful monitoring is warranted in specific high-risk populations." (PMID 40607140, 2025). "DPP-4 inhibitors also showed dose-dependent increases in beta-cell mass in a mouse model of type 2 diabetes, leading to the normalization of beta-cell mass and an improvement in islet architecture." (PMID 39430732, 2024). "Although we used DPP4 as a marker for AFECs, DPP4 is known to play an important role in the pathogenesis of type 2 diabetes." (PMID 39465352, 2024). "In a Canadian observational study including patients with type 2 diabetes, the adjusted hazard ratio for diabetic ketoacidosis vs. DPP4 inhibitor users were 2.52 (95% CI 1.23–5.14) for users of empagliflozin and 1.86 (1.11–3.10) for users of dapagliflozin." (PMID 38918063, 2024). "DPP-4 inhibitors like sitagliptin and saxagliptin improve glucose control and reduce inflammation in type 2 diabetes, potentially offering neuroprotective benefits in PD through various molecular pathways." (PMID 39594624, 2024). "In conclusion, our study provided a solid theoretical foundation for the inhibitory mechanisms of IPI, LPAVTIR, and LPPEHDWR on DPP4, offering valuable insights for advancing the development of drug targets for type 2 diabetes." (PMID 38255913, 2024). "In type 2 diabetes, use of metformin, dipeptidyl peptidase-4 (DPP-4) inhibitors and glucagon-like peptide-1 receptor agonists (GLP1-RAs) appears to be neutral/beneficial with regard to BMD and fracture risk." (PMID 38761257, 2024). "The aim of this study is to directly compare the effects of SGLT2 inhibitors and DPP-4 inhibitors on β-cell function in patients with type 2 diabetes." (PMID 39497800, 2024). "DPP-4 inhibitors are frequently used as first-line agents for the treatment of type 2 diabetes in Japan." (PMID 38256615, 2024). "Numerous studies have confirmed the role of DPP-4 in the pathophysiology of type 2 diabetes, leading to the development of various DPP-4 inhibitors." (PMID 40066124, 2024). "Propensity score (PS) matched (1:1) adults with type 2 diabetes (T2D) initiating empagliflozin (a sodium-glucose cotransporter-2 inhibitor) during 2014–2018 who were compared to those initiating a dipeptidyl peptidase-4 inhibitor (DPP-4i)." (PMID 39430801, 2024). "The development of sitagliptin, a dipeptidyl peptidase-4 (DPP-4) inhibitor for the treatment of type 2 diabetes, offers another instructive example of structure-guided bioavailability enhancement." (PMID 39684832, 2024). "Other drugs have been tested for preventing the onset of type 2 diabetes, such as voglibose, DPP-4 inhibitors, orlistat, and valsartan." (PMID 39543645, 2024). "Dipeptidyl peptidase-4 (DPP-4) inhibitors constitute a class of medications employed in the treatment of type 2 diabetes (T2D)." (PMID 39027329, 2024). "In line with the literature, these findings suggest a potential protective effect of DPP-4 inhibitors on cognitive impairment in patients with type 2 diabetes." (PMID 38510866, 2024). "In another cohort study including type 2 diabetes mellitus patients in Hong Kong, SGLT2 inhibitors were found to significantly reduce the risk of new-onset dementia compared to DPP-4 inhibitors." (PMID 39728750, 2024). "Dipeptidyl peptidase-4 (DPP-4) inhibitors, employed primarily to manage type 2 diabetes, function by inhibiting the degradation of glucagon-like peptide-1 (GLP-1), thus facilitating glycemic control." (PMID 38774880, 2024). "DPP4 inhibitors are mainly weight-neutral in patients with type 2 diabetes in combination and monotherapy clinical trials." (PMID 38003291, 2023). "Inhibitors of DPP-4 lower glucose levels in individuals with type 2 diabetes because they prevent the degradation and inactivation of the intact biologically active molecular forms of GIP and GLP-1." (PMID 37430117, 2023).
type 2 diabetes (continued). "Dipeptidyl peptidase 4 (DPP4) inhibitors, a class of small molecule inhibitors, are highly effective for treating type 2 diabetes." (PMID 37115489, 2023). "In contrast, other hypoglycemic drugs like dipeptidyl peptidase-4 inhibitors (DDP4i) and thiazolidinediones are ineffective in cardiovascular risk reduction and are even associated with increased heart failure in patients with type 2 diabetes mellitus (T2DM)." (PMID 38044371, 2023). "Development of small molecules-based approaches emerging to treat Type-II diabetes, like incorporating 2(S)-cyanopyrrolidine scaffold into a molecule, has been used often & has become a key intermediate for the synthesis of DPP-4 inhibitors." (PMID 37570832, 2023). "SGLT2-inhibitors (SGLT2-i) and DPP4-inhibitors (DPP4-i) are two commonly prescribed glucose-lowering treatment options, recommended after metformin in type 2 diabetes clinical guidelines." (PMID 37328784, 2023). "Gemigliptin (Gemiglo®, LG Life Sciences, Daejeon, Republic of Korea) is a DPP-4 inhibitor approved for use in patients with type 2 diabetes." (PMID 38258046, 2023). "A well-known example is the transmembrane form of dipeptidyl-peptidase 4 (DPP4), an important target in type 2 diabetes, which not only regulates immune cells via its enzymatic activity but also functions as a cell surface receptor." (PMID 38069440, 2023). "Glucagon-like peptide-1 receptor agonists (GLP1-RA) and dipeptidyl peptidase-4 inhibitors (DPP4i) were recently introduced as novel classes of drugs for treating patients with type 2 diabetes (T2D)." (PMID 37514043, 2023). "Several recent animal studies have shown that DPP-4 inhibitors ameliorate hepatic steatosis in an animal model of type 2 diabetes and obesity." (PMID 37739179, 2023). "Surprisingly, at admission only 2.8% of patients with type 2 diabetes were treated with DPP-4 inhibitors, 0.1% with GLP1-RA and 0.2% with SGLT2 inhibitors." (PMID 36964858, 2023). "The dipeptidyl peptidase-4 (DPP4) inhibitor sitagliptin is widely used to treat type 2 diabetes, but researchers have recently found that it also has a therapeutic effect in renal and hepatic fibrosis." (PMID 37929034, 2023). "Treatment with sitagliptin, a dipeptidyl peptidase-4 (DPP-4) inhibitor generally used to treat type 2 diabetes, seems to obviate the resistant effects induced by the circMET." (PMID 37587333, 2023). "This study aimed to investigate the association of SGLT2I use vs dipeptidyl peptidase-4 inhibitor (DPP4I) use with OAD incidence and exacerbation events in patients with type 2 diabetes." (PMID 36648944, 2023). "The ability to increase insulin secretion through the incretin effect of DPP-4 inhibitors has been described not only in type 2 diabetes but also in CFRD." (PMID 37371849, 2023). "On the other hand, DPP-4 inhibitors are generally tolerable and safe for use in older people with type 2 diabetes and, as such, they can be an important treatment option in the older/frail population where quality of life is a priority." (PMID 37433896, 2023). "The level of DPP-4 is increased in patients with type 2 diabetes and corresponds to the onset of albuminuria." (PMID 37047505, 2023). "To date, various therapeutics for type 2 diabetes have been proposed, including the inhibition of dipeptidyl peptidase-IV (DPP4)." (PMID 38004494, 2023). "Are sodium-glucose cotransporter 2 inhibitors (SGLT2Is) associated with risk of incident obstructive airway disease (OAD) and exacerbation events in clinical settings among patients with type 2 diabetes compared with dipeptidyl peptidase-4 inhibitors (DPP4Is)?" (PMID 36648944, 2023). "DPP4 inhibition has shown protective effects against type 2 diabetes and several metabolic disorders, including obesity." (PMID 37894869, 2023). "Dipeptidyl peptidase (DPP)-4 inhibitors are second- or third-line drugs commonly used in the management of type 2 diabetes (T2DM)." (PMID 37760498, 2023).
type 2 diabetes (continued). "Linagliptin is a dipeptidyl peptidase-4 (DPP-4) inhibitor used for the treatment of type 2 diabetes, with additional beneficial effects for the kidney." (PMID 36635409, 2023). "HSK7653, an oral dipeptidyl peptidase-4 inhibitor administered every 2 weeks, is a candidate for the treatment of type 2 diabetes mellitus." (PMID 37532063, 2023). "Six genes (CNR2, DPP4, GLP1R, SLC5A1, HTR2C, MCHR1) that encode therapeutic targets in development of type 2 diabetes or obesity." (PMID 36902588, 2023). "It is crucial to understand the impact of DPP-4 inhibitors on the immune system, particularly T cell differentiation, maturation, and proliferation, in patients with type 2 diabetes and CKD." (PMID 38065905, 2023). "Instead, there is a particular interest in the use of dipeptidyl peptidase 4 (DPP-4) inhibitors in hospitalized patients with type 2 diabetes for their few side effects and neutral effects on major adverse cardiovascular outcomes." (PMID 36964858, 2023). "We performed the review to assess the safety of dipeptidyl peptidase-4 (DPP-4) inhibitors in older type 2 diabetes patients with blood sugar outside the normal level." (PMID 35111291, 2022). "Treatment with GLP-1 receptor agonists was associated with lower all-cause mortality among patients with type 2 diabetes, advanced-stage CKD, and ESKD than was treatment with DPP-4 inhibitors." (PMID 35254430, 2022). "Sitagliptin is an FDA-approved, highly selective dipeptidyl peptidase-4 inhibitor used to treat Type 2 diabetes." (PMID 35217718, 2022). "DPP-4 inhibition by sitagliptin, an approved agent for the treatment of patients with type 2 diabetes, has previously been shown to alleviate pulmonary vascular remodeling in monocrotaline (MCT)-induced PH rats." (PMID 35130955, 2022). "Studies have demonstrated that immune cells, especially circulating CD4+ T helper cells, are important source of plasma DPP4 activity which is responsible for postprandial glucose intolerance in patients with type 2 diabetes." (PMID 35309368, 2022). "Sitagliptin is a promising dipeptidyl peptidase 4 (DDP-4) inhibitor developed by MERCK for the treatment of type II diabetes." (PMID 34964708, 2022). "This is particularly important as DPP-4 inhibitor in combination with metformin is currently the most widely prescribed combination for type 2 diabetes, owing to additional benefits such as increased efficacy, tolerability, and lowered risk of hypoglycemia." (PMID 35928902, 2022). "It is an anti-diabetic drug used in the treatment of type 2 diabetes and it belongs in the class of dipeptidyl peptidase-4 (DPP-4) inhibitors." (PMID 36500672, 2022). "DPP4 inhibitors, which are successful type 2 diabetes drugs, prevent inactivation of secreted GLP-1." (PMID 36343264, 2022). "The search was for randomized, controlled trial studies (RCT) on insulin infusion (CSII) combined with oral hypoglycemic drugs (TZDs/metformin/acarbose/GLP-1 receptor agonist/SGLT-2 inhibitor/DPP-4 inhibitor) in the treatment of type 2 diabetes." (PMID 36015100, 2022). "DPP4 inhibitors have been shown to control blood glucose levels and prevent the exacerbation of cognitive impairment in older type 2 diabetes patients with mild cognitive impairment." (PMID 35646138, 2022). "In the type 2 diabetes group, 12 participants were treated with metformin, while five received dipeptidyl peptidase 4 (DPP4) inhibitors and one was treated with glimepiride." (PMID 35275239, 2022). "The incidence of major adverse limb events was also lower in patients with type 2 diabetes receiving GLP-1 receptor agonists compared with those receiving DPP4 inhibitors." (PMID 35996159, 2022). "The studies that have been conducted so far suggest that the use of DPP-4 inhibitors as a monotherapy or combination therapy is an effective strategy for type 2 diabetes." (PMID 36005129, 2022). "Sitagliptin is the dipeptidyl peptidase 4 (DPP-4) inhibitor that is most commonly prescribed to treat type 2 diabetes." (PMID 35163991, 2022).
type 2 diabetes (continued). "In a retrospective clinical study, anti-DPP4 inhibitors were found to decrease the risk of HCC in patients with chronic hepatitis C infection and type 2 diabetes mellitus (T2DM)." (PMID 36611926, 2022). "In the current research paper, we tried to evaluate the in silico activity of photochemicals against the major targets (DPP4 and amylin) of type II diabetes involved in diabetic nephropathy." (PMID 35956932, 2022). "The detected DPP4 concentration correlated well with the results from the ELISA kit and a higher DPP4 activity in blood plasma samples from type II diabetes patients was clearly confirmed." (PMID 35425010, 2022). "In several scientific studies, we note that it has been suggested that heartwood extract of P. marsupium has dipeptidyl pepdase-4 (DPP-4) inhibition properties in the treatment of type-2 diabetes and Alzheimer’s disease." (PMID 35161227, 2022). "According to research, GLP-1R agonists (GLP-1RAs) have a greater impact on hemoglobin A1c (HbA1c), fasting plasma glucose (FPG), blood lipids, and body weight in patients with type 2 diabetes than DPP4 inhibitors." (PMID 35736482, 2022). "Dipeptidyl peptidase-4 inhibitor for treating type 2 diabetes mellitus, compounds (versions)//Patentee: Neobiotek LLC (Moscow, Russia)." (PMID 35337071, 2022). "We aimed to assess the safety of dipeptidyl peptidase-4 (DPP-4) inhibitors in older patients with type 2 diabetes with inadequate glycaemic control." (PMID 35111291, 2022). "As another example, DPP4 activity was found to be higher in mice fed with a high fat diet (HFD) compared to normal fed mice and blood samples from type II diabetes patients had also a higher DPP4 activity than healthy individuals as controls." (PMID 35425010, 2022). "The hormone glucose-dependent insulinotropic polypeptide (GIP), which is elevated by dipeptidyl peptidase-4 (DPP-4) inhibitors (incretin-related drugs) for the treatment of type 2 diabetes, has been shown to suppress inflammation in experimental periodontitis." (PMID 36294882, 2022). "DPP-4 inhibitor, launched and wildly used in clinical practice, was proven to improve BMD and decrease the risk of fracture in type 2 diabetes, establishing a relationship between DPP-4 and bone quality." (PMID 35139864, 2022). "DPP-4 inhibitors are the most commonly prescribed first-line drugs for patients with type 2 diabetes in Japan." (PMID 36078917, 2022). "GLP-1 receptor agonists (GLP-1RAs) and DPP4 inhibitors are incretin-based therapies for type 2 diabetes and are critical second-line drugs for the treatment of T2D." (PMID 35736482, 2022). "We will use this method to compare SGLT2 inhibitors, GLP1 receptor analogues and DPP4 inhibitors in type 2 diabetes." (PMID 36302574, 2022). "DPP4 inhibitors have become important drugs for the treatment of type 2 diabetes due to the improved regulation of glycemia through the increased glucagon-like peptide-1 levels." (PMID 35884882, 2022). "Our study is the first network meta-analysis to address the effects of SGLT-2 inhibitors, GLP-1 agonists, and DPP-4 inhibitors on kidney outcomes in participants with type 2 diabetes." (PMID 35421174, 2022). "Dipeptidyl peptidase 4 (DPP4) inhibitors can treat type 2 diabetes by slowing GLP-1 degradation to increase insulin secretion." (PMID 35629891, 2022). "The enzyme dipeptidyl peptidase-4 (DPP-4) is a key component in regulating the glucagon-like peptide-1 (GLP-1) type 2 diabetes." (PMID 36005129, 2022). "Clinical studies have assessed the efficacy of multiple DPP‐4 inhibitors in type 2 diabetes mellitus (T2DM)." (PMID 36515221, 2022). "One-third to one-fourth of patients had taken dipeptidyl peptidase-4 inhibitors, and/or metformin and/or sodium-glucose co-transporter 2 inhibitors as the treatment for type 2 diabetes." (PMID 35203610, 2022). "Sitagliptin is a drug used to treat type 2 diabetes, specifically to inhibit dipeptidyl peptidase 4 (DPP-4)." (PMID 35385679, 2022).